IL1B (interleukin 1 beta)
Diseases named in the same sentence as IL1B in open-access papers (continued):
Sharing a sentence is not in itself a finding about the gene and the disease.
COVID-19 (continued). "Adult acute COVID-19 patients exhibited significantly increased cytokine/chemokine levels compared to healthy controls and SARS-CoV-2 mRNA vaccinees for 9 of 10 of the markers measured, but not IL-1β." (PMID 39494457, 2024). "The phenomenon, called post-acute sequelae of COVID-19 (PASC), may be more closely linked to persistent cytokine dysregulation, including sustained IL-1β activity and elevated levels of IL-6 and TNF-α, rather than the emergence of post-COVID-19 autoantibodies." (PMID 39518964, 2024). "In addition, procalcitonin, IL-6, IL1B, INF γ, IP10, and MCP1 serum, and LDH, which were reported earlier as significant predictors for the severity of COVID-19 were not investigated in the current study." (PMID 38130539, 2023). "Moreover, exosomes from patients with severe COVID-19 (but not light COVID-19 or healthy donors) induced the expression of NLRP3, pro-caspase-1 and pro-IL-1β in human endothelial cells, microvascular endothelial cells and liver endothelial cells." (PMID 38439942, 2023). "In most patients with severe COVID-19, the serum cytokines including IL-6, IL-2, IL-10, and TNF-α were elevated; however, there was no significant change in the secretion of IL-1β in asymptomatic patients and those with mild infections in the early stage, in some cases." (PMID 38004809, 2023). "In fact, a few studies reported a decrease in IL-1β and/or TNF-α but not IL-6, which explains why IL-6 could be the sole determinant of severity in COVID-19." (PMID 37106750, 2023). "Moreover, in our cohort group, IL-1β, IL-7 and FGF-2 elevated in samples from patients with severe, but not with moderate COVID-19 compared to HDs." (PMID 36012146, 2022). "After stimulation with human rIL6, there was no significant increase in IL-1β, IL-6 or IFN-γ lymphocyte or monocyte producers, suggesting that human rIL-6 in COVID-19 patients may not induce the synthesis of proinflammatory cytokines by circulating leucocytes." (PMID 35901034, 2022). "On admission, there were higher serum concentrations of tumor necrosis factor α (TNFα) (p < 0.001), interleukin 1 β (IL-1β) (p < 0.001), pentraxin 3 (PTX3) (p < 0.001), resistin (p = 0.032), and lower concentrations of adiponectin (p < 0.001) between the severe COVID-19 and the non-severe patients." (PMID 36289725, 2022). "In addition to IL-6, the serum levels of IL-2R, IL-10, IL-1β, IL-4, IL-8, IL-17 and TNF-α were also elevated in both severe and non-surviving COVID-19 patients." (PMID 35237162, 2022). "Furthermore, NLRP1-dependent pyroptosis is sufficient to cause progressive lung injury, independent of NLRP3 activation or IL-1b secretion, which suggests a relevant role of DPP9 in mediating lung injury seen in severe COVID-19." (PMID 34027315, 2021). "Serum inflammatory factor levels of IL-2, IL-1β, IL-5, IL-4, IL-6, IL-8, IL-10, IL-17, IL-12P70, IFN-α, TNF-α, IFN-γ, endotoxin, CRP, and hs-CRP of non-severe COVID-19 patients across different age groups (< 50, 50–60, 60–70, and ≥ 70 years) were not significantly different." (PMID 33065551, 2020). "Apart from those particular features, COVID-19 and non-COVID-19 ARDS share the well-known involvement of both IL-8 and IL-1β within the airway, potentially driven by the release of endogenous mediators originating from injured alveolar cells (e.g., mitochondrial alarmins)." (PMID 33138839, 2020). "However, also non-ICU patients (n = 28) showed increased plasma levels of IL-1β, IFN-c, IP-10, MCP-1, IL-4, and IL-10 even if the “cytokine storm” was higher in patients with a severe COVID-19." (PMID 33633566, 2020). "Clinical evaluation of 41 COVID-19 patients (Non-ICU: 28 and ICU: 13) for over 26 chemokines and cytokines revealed increased levels of 16 of them such as IL-1β, IL-1RA, IL-17, IL-8, IL-9, IL-10, basic FGF, G-CSF, GM-CSF, IFN-γ, CXCL10, CCL2, CCL3, CCL4, PDGF, TNF-α." (PMID 33335518, 2020).
COVID-19 (continued). "Another study that compared PCC patients with patients who had COVID-19 but did not present PCC, and patients who had PCC and recovered, showed that ongoing PCC could be characterised by higher circulating IL-1β, IL-6 and TNFα, 8 to 10 months after acute infection." (PMID 38549752, 2024). "In addition, we could not demonstrate correlation between severity of COVID-19 and other established ARDS-related cytokines such as TNF-α, IL-1α, and IL-1β." (PMID 34938289, 2021). "Finally, in both COVID-19 and non-COVID-19 patients, higher mitochondrial DNA concentrations in the plasma and ELF compartment were highly correlated with alveolar inflammation, as assessed by BALF cell count and ELF IL-8 and IL-1β concentrations." (PMID 33138839, 2020).
Obesity (1,034 papers, 2007 to 2026). Accumulation of substantial excess body fat. "In our analysis of inflammatory cytokine levels, we found that CCPP intervention reduced the concentrations of pro-inflammatory factors (TNF-α, IL-1β, and IL-6) and alleviated inflammatory responses associated with obesity development." (PMID 41596915, 2026). "Obesity is generally associated with elevated IL-6, IL-1β, and IFN-γ levels due to an increased M1 macrophage population and chronic low-grade inflammation." (PMID 41596532, 2026). "In particular, IL-1β plays a central role in chronic inflammation underlying insulin resistance and glycemic dysregulation in obesity and T2D." (PMID 40943225, 2025). "In this nested case–control study of Mediterranean individuals with overweight/obesity and MetS, higher baseline concentrations of IL-6, IL-1ra, TNFα, and IL-1β were associated with an increased risk of incident CKD after one-year follow-up." (PMID 40867871, 2025). "Together, these findings suggest a potential association between obesity and enhanced innate immune responses in equine asthma, reflected by elevated circulating IL-1β levels and increased neutrophil counts." (PMID 40646891, 2025). "We provide evidence of the important role of IL-1β in obesity-associated CC by directly promoting inflammation." (PMID 39305371, 2025). "The NLRP3 inflammasome has emerged as a major therapeutic target to limit pro-inflammatory IL-1β activity in obesity-associated metabolic disorders." (PMID 39532538, 2025). "Inflammation assessment showed that WMSZY markedly suppressed TNF-α and IL-1β expression in eWAT, both of which are closely associated with obesity-related chronic low-grade inflammation." (PMID 41194880, 2025). "Further studies to understand how IL-1β modulates the carcinogenic process in obesity-associated CC and to establish a relation between IL-1β and cancer prognosis are warranted." (PMID 39305371, 2025). "The determination of the circulating levels of IL-1β in the animal model would contribute to better elucidate the role of weight loss in the regulation of this protein in the context of obesity and CC development." (PMID 39305371, 2025). "Interleukin (IL)-1β is a pro-inflammatory cytokine relevant in obesity-associated chronic inflammation and tumorigenic processes." (PMID 39305371, 2025). "Lipopolysaccharide (LPS, endotoxin) -mediated signaling of caspase-4 (human) and -11 (rodent) can induce the maturation of inflammatory cytokine IL-1β and cell pyroptosis, which is associated with the pathophysiology of many diseases such as obesity." (PMID 40356927, 2025). "MCP-1 and TNF-α play crucial roles in the relatively early stages of inflammation associated with obesity, whereas IL-6 and IL-1β are potentially involved in the later phases of inflammation." (PMID 39803918, 2025). "The effect of weight loss on the gene expression levels of Il1b was studied in the intestinal tract of a rat model with diet-induced obesity (DIO)." (PMID 39305371, 2025). "IL1B, a key inflammatory regulator, has been associated with cardiovascular risks induced by obesity and is considered a targeted therapy for metabolic syndrome." (PMID 40376303, 2025). "Obesity is a chronic disease associated with systemic inflammation caused by excess visceral fat and pro-inflammatory cytokines such as IL-1β and IL-6." (PMID 41422827, 2025). "Elevated levels of IL-1β have been associated with various diseases, including obesity, cardiovascular diseases, cancer, and periodontitis." (PMID 40311089, 2025). "Taken together, here we show that IL-1β contributes to the inflammatory milieu in obesity-associated CC, demonstrated by its upregulation in both the VAT from patients with OB and CC and in the colon tissue from patients with CC." (PMID 39305371, 2025).
Obesity (continued). "While obesity is associated with increased production of pro‐inflammatory cytokines like TNFα and IL1β, it is less clear how age and duration of HFD affect inflammation in the visceral adipose tissue of female mice." (PMID 39230054, 2024). "In READ, IL-1β expression was also associated with obesity, with higher levels observed in obese patients compared to normal-weight patients." (PMID 39766795, 2024). "In fact, islets highly express the IL-1 receptor type 1 (IL-1R1), making them more sensitive to IL-1β and susceptible to obesity-induced inflammation." (PMID 38794702, 2024). "Serum TNF-α and IL-1β levels of rats were also analyzed in order to evaluate chronic inflammation associated with obesity." (PMID 39055496, 2024). "Pro-inflammatory interleukin-β (IL-1β) is a significant cytokine mainly produced by macrophages that plays a role in the development of obesity-associated insulin resistance." (PMID 38178093, 2024). "SM was also demonstrated to have inhibitory effects on obesity-induced growth and ROS production associated with decreased production of proinflammatory IL-6 and IL-1β in HepG2 cells exposed to sera from obese individuals." (PMID 38247522, 2024). "IR can instigate an upsurge of inflammatory cytokines associated with obesity, including IL-1β, IL-2, IL-4, IL-5, IL-6, IL-8, tumor necrosis factor-α, and interferon, which have been robustly linked to the development of PAH." (PMID 38702735, 2024). "Proinflammatory cytokines like TNFα, interleukin-1β (IL-1β), and IL-6, produced primarily by macrophages infiltrating adipose tissue due to obesity, are linked to insulin resistance and MetS features." (PMID 38999869, 2024). "TNFα, IL-1β, IL-6, or IL-8 are proinflammatory cytokines that are considered obesity-linked inflammatory cytokines, predominantly in the abdominal fatty tissue." (PMID 39057082, 2024). "Macrophages secrete multiple factors, such as osteopontin, IL-1β, and IL-6, which have been implicated in enhancing adipose tissue fibrosis, although less is known about the impact of obesity on macrophage function within tumors." (PMID 37296891, 2023). "Obesity is often associated with low grade inflammation and elevated levels of various pro-inflammatory factors, including TNFα, IL-6, IL-1β and MCP-16." (PMID 37386070, 2023). "IL-1β, IL-6, and TNF-α are classical pro-inflammatory cytokines associated aging and obesity, the levels of IL-1β, IL-6, and TNF-α in serum were significantly decreased in the Y-ASC transplantation group when compared to the old control group." (PMID 37533129, 2023). "The level of inflammatory factors like IL-1β correlated with obesity of PCOS patients, and PCOS patients who carried T allele of IL-1β gene promoter region (-511) were at high risk of obesity." (PMID 37693353, 2023). "Obesity is associated with low-grade inflammation, characterized by the release of pro-inflammatory cytokines including TNFα, IL-1β, and IL-6." (PMID 37373472, 2023). "For instance, leptin and adiponectin contribute to body weight regulation, while TNF-α, IL-6, and IL-1β are associated with local inflammation resulting from obesity." (PMID 37408757, 2023). "Previous studies supported that proinflammatory cytokines (including TNF and IL-1β) from adipose tissue have been implicated in the association between obesity and osteoarthritis." (PMID 36918849, 2023). "The plasma concentration of IL-1β is elevated in obese individuals, and obesity causes cognitive disorders by promoting the inflammation of the central nervous system." (PMID 37371369, 2023). "Increased circulating levels of IL-1β are a hallmark of the chronic, low-grade inflammation associated with obesity and related diseases." (PMID 36831188, 2023). "In fact, in adipose tissue, the M1 macrophages secrete high levels of pro-inflammatory cytokines (TNF-α, IL-6 and IL-1β), inducing an inflammation state and an impairment of insulin sensitivity, typically associated with obesity." (PMID 37447161, 2023).
Obesity (continued). "Recent studies demonstrate that IL-1β cytokine is closely associated with inflammation, hepatic injury, and obesity." (PMID 36899958, 2023). "The levels of inflammatory cytokines (including TNF-α, IL-1β)—that are parameters associated with obesity—are also related to the severity of depression." (PMID 37049434, 2023). "The intracellular contents released by accumulated ACs further trigger an immune response and lead to a release of inflammatory factors, such as TNF-α, IL-1β, and IL-6, which induce the dysfunction of chondrocyte homeostasis in obesity-associated OA." (PMID 37144868, 2023). "Recently, Tet2 loss-of-function mutations have been shown in mice to increase IL-1β secretion from adipose tissue and aggravate age- and obesity-related insulin resistance." (PMID 36835370, 2023). "As a result, proinflammatory cytokines, such as interleukin-1beta (IL-1β) and interleukin-1sigma (IL-1σ), are generated, and these have been linked to the onset of obesity-related insulin resistance." (PMID 36839178, 2023). "The expression of IL-1β and IL-6, which are involved in chronic inflammation associated with obesity, was also significantly decreased in cells treated with transgenic rice seed extracts." (PMID 37631337, 2023). "Production of pro-inflammatory cytokines, including IL-1β and IL-6, has been linked to obesity’s pro-inflammatory response." (PMID 37175603, 2023). "IL-1β is capable of influencing many consequences in obesity-associated NASH patients that can lead to HCC development, as shown herein." (PMID 36289606, 2022). "Obesity was associated with an upregulation in the gene expression of IL-1β (p < 0.05), IL-6 (p < 0.01) and NOX-4 (p < 0.05), and with a downregulation in the mRNA levels of the antioxidant enzymes GPX-3 and SOD-1 (p < 0.01 for both) in aortic tissue." (PMID 36009292, 2022). "Regarding inflammatory markers, which were studied since obesity is linked with a chronic low-grade inflammatory state, a moderate decrease in IL-1β levels and a significant decrease in TNF-α levels in participants of the PB group over time were observed." (PMID 35745249, 2022). "It is now widely accepted that IL-1β signaling plays a key role in the development of obesity, IR, and T2D risk." (PMID 35276849, 2022). "Taken together, these results support the idea that neutrophils penetrate AT, causing high numbers of ATMs and IL-1b levels to drive obesity and insulin resistance." (PMID 36479119, 2022). "The interleukin-1 (IL-1) family, particularly IL-1β, is a group of cytokines that play a central role in the regulation of responses associated with immune and obesity-associated inflammation." (PMID 35433780, 2022). "A previous study revealed that obesity-associated NLRC4 inflammasomes mediated IL-1β release, which promotes the growth of breast cancer by triggering VEGF production and angiogenesis." (PMID 35928454, 2022). "Considering the importance of IL-1β and IL-18 in obesity-associated NASH and, consequently, in HCC progression, their therapeutic exploration appears to be promising for the management of this lethal cancer." (PMID 36289606, 2022). "From the onset, obese mice exhibited high levels of blood monocytes, which is in accordance with observations of monocytosis in obesity caused by IL-1β production of the adipose tissue." (PMID 34867969, 2021). "As mentioned, because it produces oxidative stress and causes inflammatory conditions, obesity is one of the factors that increases the basal levels of IL-6, IL-1β, and fibrinogen and reduces anti-inflammatory markers such as IL-10 and nesfatin-1." (PMID 33997019, 2021). "Obesity can cause immune-inflammation by activating macrophages, and activate IL-1β and NF-κB pathway." (PMID 34026868, 2021).
Obesity (continued). "A KO of the IL1 receptor type 1 gene (Il1r1), which codes for a receptor of IL-1α, IL-1β, and IL-1RN, causes maturity onset obesity on a normal diet but reduces local adipose-tissue inflammation on an HFD despite almost unchanged immune-cell recruitment." (PMID 34834553, 2021). "Previously, elevation of IL-1β has been regarded as an indicator of inflammation and has been shown to be associated with obesity-induced insulin resistance." (PMID 33642989, 2021). "Recent studies in humans have linked HMOX2, Nrf2, and IL-1β with insulin resistance and obesity, which are two characteristics exhibited by fasting NES." (PMID 34744798, 2021). "It has been described that proinflammatory cytokines such as tumor necrosis-alpha (TNF-α), interleukin (IL)-1β and IL-6 play a central role in cardiac damage associated with ischemic conditions and obesity, as well." (PMID 34439522, 2021). "Systemic inflammation is a common characteristic linking obesity, metabolic syndrome and elevated cardiovascular risk, 22 with highlighted role for IL-1β and NLRP3 inflammasome." (PMID 33542047, 2021). "The increase in adiponectin, an inflammatory adipocytokine, such as TNFα, IL-1β, and IL-6, has a large effect on the renal disorders associated with obesity, causing an increase in the mesangial matrix and inflammation of the renal tubular epithelium." (PMID 34959901, 2021). "Along these lines, intracerebral delivery of IL-1 receptor antagonist (IL-1ra) restrains hippocampal inflammation, synaptic dysfunction and cognitive impairment, indicating that IL-1β mediates obesity-associated deterioration of hippocampal function." (PMID 34201844, 2021). "Histological staining results suggested that IL-1β shRNA/yeast can improve joint damage caused by obesity during weight loss." (PMID 34683827, 2021). "In conclusion, this study showed that IL-1β shRNA/yeast can effectively reduce body weight and further alleviate the articular cartilage degeneration caused by obesity." (PMID 34683827, 2021). "In BAT, macrophage infiltration contributes to the high levels of inflammatory cytokines (TNF, IL-6, and IL-1β) in conditions associated with AT hypertrophy such as high fat diet or obesity." (PMID 32934774, 2020). "We also measured serum concentrations of TNF-α and IL-1β as obesity is highly associated with systemic inflammation." (PMID 33408699, 2020). "Obesity elevated levels of C reactive protein and IL-1β in the blood, just increasing the development risk of T2DM." (PMID 32938466, 2020). "IL-1β is the major pro-inflammatory cytokine produced by ATMs and it is implicated in the development of obesity-associated insulin resistance." (PMID 33260769, 2020). "The loss of the NLRC4 inflammasome or inhibition of IL-1β is sufficient to abolish the increased tumor progression in obese mice, providing strong evidence that obesity-associated inflammation drives breast cancer progression." (PMID 32630445, 2020). "As obesity also causes low‐grade chronic inflammation, we investigated the expression of the inflammation markers Tnfα, Il‐1β, and Il‐6 in subcutaneous and epigonadal fat." (PMID 32537550, 2020). "Inflammatory factors IL-1β and IL-1ra had correlation with obesity of PCOS patients; PCOS patients who carried T allele of IL-1β gene promoter region (-511) and V allele of IL-1ra gene were at high risk of obesity." (PMID 32454906, 2020). "As expected, obesity was associated to increased inflammation of the ileum, as revealed by the significantly higher mRNA expression level of Il1b, Ccl2 and, to a lesser extent, of Il6." (PMID 32244932, 2020). "This leads to a NLRC4/IL-1β dependent upregulation of adipocyte derived angiopoietin-like 4 and enhanced obesity associated tumor angiogenesis." (PMID 33339340, 2020).